BRCA1 (BRCA1 DNA repair associated)
Diseases named in the same sentence as BRCA1 in open-access papers (continued):
Sharing a sentence is not in itself a finding about the gene and the disease.
breast cancer (continued). "Recent preclinical and clinical studies demonstrate the efficacy of Poly ADP-ribose polymerase (PARP) inhibitors such as Olaparib, Talazoparib, Niraparib as monotherapy for patients with breast cancer susceptibility gene 1/2 (BRCA1/2)-mutated ovarian and breast cancers including TNBC." (PMID 36130940, 2022). "The BRCA1 lack in breast cancer was associated with increased glycolytic metabolism than BRCA1-WT." (PMID 35211121, 2022). "In light of these observations, we may hypothesize that SNPs found to be associated with increased NBR2 expression could be associated with downregulation of BRCA1 and hence with breast cancer risk." (PMID 35333900, 2022). "In a cohort of 560 patients suffering from breast cancer, HRDetect could identify and, importantly, discriminate between BRCA1/2-deficient tumors with a sensitivity of 98.7%, using a probabilistic cutoff of 0.7." (PMID 36077694, 2022). "The most common prognostic indicators of breast cancer are BRCA1 mutations, especially for early diagnosis, and they serve as a predictive biomarker for almost 80% of patients with combined ovarian and breast cancer and up to 20% of women with a family history of breast cancer." (PMID 35163783, 2022). "Furthermore, approximately 10% of patients with TNBC have BRCA1/2 mutation, which has the highest incidence among breast cancer subtypes." (PMID 35626017, 2022). "Carriers of BRCA1/2 pathogenic variant carriers and their relatives have an increased risk of breast cancer due to their genetic predisposition and are a well-established sub-group of individuals with needs for targeted prevention and care pathways based on a risk-based approach." (PMID 35327984, 2022). "Additionally, a well-characterized BRCA1-deficient breast cancer cell line was also more prone to cisplatin-induced senescence than a BRCA1-proficient counterpart." (PMID 35082152, 2022). "Additionally, BRCA1-mutated breast cancer also shares phenotypic similarities such as morphology, molecular subtype, and responsiveness to poly-(adenosine diphosphate-ribose) polymerase inhibitors (PARPi) treatment." (PMID 36298462, 2022). "In our sample, we had a higher percentage of BRCA2 mutation carriers; this result is interesting, since usually, BRCA1 shows a higher incidence compared to BRCA2, with a lifetime risk of developing breast cancer of 65% for BRCA1 mutation carriers and of 40% in patients with BRCA 2 mutation." (PMID 35573021, 2022). "Thus, in the human population, variation in the enhancer region of PLK1 appears to specifically modify breast cancer risk for BRCA1 mutation carriers." (PMID 35459234, 2022). "However, emerging evidence suggests that a subset of BRCA1/BRCA2 wild-type breast cancer patients can also have deficiencies in homologous recombination." (PMID 35884530, 2022). "The most notable mutations in breast cancer occur in the BRCA1 and BRCA2 genes." (PMID 35764927, 2022). "The functional connection between CDK5RAP3 and breast cancer may be extended to cancer etiology, as suggested by the results of the association study between common genetic variants and cancer development in BRCA1/2 mutation carriers." (PMID 35053516, 2022). "We also observed that breast cancer patients exposed to pesticides had a higher mutational burden when diagnosed before 50 years old (p = 0.00978) and/or when carrying BRCA1 (p = 0.0138), BRCA2 (p = 0.0366), and/or PALB2 (p = 0.00058) variants, a result not found in the unexposed group." (PMID 35875117, 2022). "Indeed, PARPi has been found to enhance the clinical outcomes of breast cancer patients with BRCA1/2 germline or somatic mutations, which have been found to improve survival and quality of life." (PMID 36140751, 2022). "•Contralateral breast cancer (CBC) risk is high in BRCA1/2 mutation carriers." (PMID 34929424, 2022). "The approximate risk of breast cancer is 65–79% with BRCA1 PV and 61–77% for BRCA2 PV11." (PMID 35469032, 2022).
breast cancer (continued). "Thus, the frequencies of CDH1 and BRCA1 mutations were slightly higher than in larger breast cancer cohorts, probably due to random variation within our sample set." (PMID 35948919, 2022). "Most BRCA1 mutation–related breast cancers are in the TNBC category, which is difficult to treat." (PMID 35025764, 2022). "The effect of hyaluronan-mediated motility receptor (HMMR) expression in BRCA1-associated breast cancer risk remains unknown." (PMID 35393420, 2022). "The ability of combined EZH2/ATM inhibition to propagate DNA damage in BRCA1-deficient breast cancer could enhance the response to immuno-oncological treatment." (PMID 35715861, 2022). "To further validate the possibility of the basal compartment being a significant contributor in BRCA1-mutation associated breast cancer, we determined the number of enhancers that were in proximity to 123 SNPs involved in ER-negative breast cancer as discovered by GWAS." (PMID 35118379, 2022). "Moreover, they are associated with the basal-like breast cancer subtype and thus independently of the BRCA1/2 status." (PMID 36555812, 2022). "Some significant external factors that run the risk of inducing breast cancer include: genetic susceptibility (e.g., mutations in BRCA1/2 and other genes), obesity, a familial history of breast cancer, unhealthy behavioural choices, hormonal contraception and treatment after menopause." (PMID 35419411, 2022). "To investigate whether MYC directly controls immune cell tumor infiltration in vivo, we assessed the effects of MYC-activation or -inactivation in established BRCA1-deficient mouse mammary tumors in situ." (PMID 36323660, 2022). "The prognostic role of BRCA1/2 mutational status in breast cancer patients is unclear." (PMID 35409110, 2022). "Therefore, active genetic testing to identify BRCA1/2 mutation carriers at the onset of breast cancer and continuous long-term monitoring of these patients can provide opportunities to detect BRCA-mutated PC at a resectable stage." (PMID 35761384, 2022). "While obesity and hyperinsulinemia are well established risk factors for breast cancer, and given the fact that BRCA1 exhibits a number of metabolic types of action, it is of medical relevance to explore the effects of a defective BRCA1 pathway on the linkage between diabetes and breast pathologies." (PMID 35432218, 2022). "The aim of the study is to compare the outcomes of implant and synthetic TIGR mesh-based breast reconstructions in breast cancer patients and women, who have higher lifetime risk for breast cancer, with mutated (changed) copy of genes: BRCA1, BRCA2, PALB2 or CHEK2." (PMID 35804960, 2022). "It is also possible that inherited rare mutations implicating in breast cancer risk, such as BRCA1 and BRCA2 germline mutations, could explain part of the variance in the MRSs." (PMID 35681745, 2022). "Here the authors show that Brca1 deficiency in preclinical breast cancer models is associated with the accumulation of myeloid derived suppressive cells and resistance to immune checkpoint blockade, that could be overcome by targeting S100A9 and CXCL12." (PMID 35304461, 2022). "Female carriers of BRCA1 mutations possess high breast cancer risk, which may reflect deficient growth control of mammary progenitor cells." (PMID 35459234, 2022).
breast cancer (continued). "Thus, our observation that BRCA1/2 germline mutations are enriched in Chinese breast cancer patients with a positive family history of cancer is consistent with patterns observed in other studies." (PMID 35494038, 2022). "Since PARP-1 inhibitors result in synthetic lethal effects, specifically in BRCA-mutated cells, MDA-MB-436 (BRCA-1-mutated breast cancer cell line) was selected to conduct a cell proliferation assay for the analogs that exhibited the most active inhibition effect against the PARP-1 enzyme." (PMID 35956876, 2022). "In agreement with our findings, other authors reported that high levels of the AKT1 isoform could be related with the loss of BRCA1 expression and HR inhibition in breast cancer models, suggesting that a similar mechanism could be possible in HGSOC." (PMID 35053468, 2022). "It is unknown whether breast cancer patients who carry pathogenic variants (PVs) in BRCA1 and/or 2 (BRCA1/2) or other cancer-associated genes receive different chemotherapy regimens than noncarriers." (PMID 35723570, 2022). "According to previous studies, OLA1 can interact with BRCA1 to regulate the centrosome number, which promotes the proliferation of breast cancer cells; OLA1 deficiency causes p21 accumulation which leads to stunted growth and frequent perinatal lethality in mouse embryonic development." (PMID 35440019, 2022). "Effective in vivo anti-tumor activity of combined GSK126 and cisplatin treatment also enhanced overall survival of mice bearing BRCA1-deficient mouse mammary tumors, suggesting that EZH2 inhibition enhances the sensitivity to platinum drugs in EZH2-overexpressing breast tumors." (PMID 35715861, 2022). "Additionally, 5q13 lesions have been identified as a molecular target for increased risk in lung cancer and are a common anomaly in breast cancer patients harboring BRCA1 mutations." (PMID 35625354, 2022). "Testing for BRCA1/2 pathogenic variants is recommended for women aged ≤45 years with breast cancer." (PMID 35312162, 2022). "Finally, it is worth noting that the PARP inhibitor olaparib has a more favorable effect on BRCA1-mutated patients in the clinical treatment of breast cancer, but the BRCA1-mutated patients account for only a portion of the population." (PMID 35563196, 2022). "BRCA1/2 mutations are responsible for almost half of hereditary breast cancers." (PMID 35373393, 2022). "We aimed to determine whether germline BRCA1/2 mutations are associated with cardiac dysfunction in breast cancer survivors." (PMID 35242827, 2022). "Notably, the HR for deletions in BRCA1 suggested an elevated breast cancer risk estimate (hazard ratio (HR) = 1.21), 95% confidence interval (95% CI = 1.09–1.35) compared with non-CNV pathogenic variants." (PMID 36203093, 2022). "To determine whether immunosuppressive TAMs are more predominant in BRCA1-deficient breast cancers than in ovarian cancers, we compared treatment-naïve mouse breast and ovarian BRCA1-deficient tumors." (PMID 35641483, 2022). "Moreover, BRCA1 germline mutations affect tumor initiation, progression, and metastasis in breast cancer." (PMID 35626017, 2022). "Interestingly, several micro RNAs were also proved to associate with BRCA1 mutation in breast cancer." (PMID 36280829, 2022). "Breast cancer risk for carriers of BRCA1 pathological variants is modified by genetic factors." (PMID 35393420, 2022). "Interestingly, defect in the HRR pathway in patients with sporadic breast cancer can mimic the phenotype of familial BRCA1 and BRCA2 mutation carriers which is termed as BRCAness." (PMID 35715772, 2022). "This theory was already explored in Ewing sarcoma and BRCA1/2-deficient breast cancer patients." (PMID 36533080, 2022).
breast cancer (continued). "We provide a rationalized approach of a synergistic therapy with EZH2 and ATM inhibition in BRCA1-deficient breast cancer that could guide further preclinical and clinical investigations." (PMID 35715861, 2022). "Other significant pathways included pathways implicated in breast cancer, among them: actin cytoskeleton, the role of BRCA1 in DNA damage response, paxillin, UVA-induced MAPK, aryl hydrocarbon receptor, ILK, and the molecular mechanisms of cancer-signaling pathways." (PMID 36360779, 2022). "In addition to BRCA1/2 mutations, other genetic risk factors for breast cancer are also associated with CBC risk." (PMID 36271417, 2022). "Dosing this panel of antigens (OVALife test) provides a reliable screen of patients at high risk, such as women younger than 50 years old with positive familiarity for ovarian or breast cancer, particularly if they bear a BRCA1 or BRCA2 gene mutation or belong to families with Lynch 2 syndrome." (PMID 35954427, 2022). "BRCA1 is frequently down-regulated in breast cancer, the underlying mechanism is unclear." (PMID 35280675, 2022). "The difference in the epigenomic landscape between BRCA1 mutants and non-carriers may be important for explaining the high propensity of BRCA1 mutation carriers for breast cancer." (PMID 35118379, 2022). "Therefore, HMMR expression in breast tumors correlates with gene sets predicted to influence BRCA1-associated breast cancer risk." (PMID 35393420, 2022). "A highly positive correlation between PARP1 expression and PARPi resistance previously has been demonstrated in breast cancer cell lines, wherein the BRCA1-mutated cell line HCC1937 had both the highest level of PARP1 expression and greatest resistance to PARPi82." (PMID 36344544, 2022). "Therefore, drugs targeting this pathway have been developed as a novel strategy for treating breast cancer in patients with BRCA1/2 mutations." (PMID 34467476, 2022). "Notably, in BRCA1/2-deficient breast cancer cells, the loss of fork remodelers protected replication forks from collapse, rescued genome stability, and induced resistance to PARPi." (PMID 36253861, 2022). "Seven in 19 relatives of patients who had BRCA1/2 gene mutations received genetic counseling for the risk of ovarian and breast cancer, in addition to screening methods and prophylactic measures according to the recommendation of the National Comprehensive Cancer Network (NCCN)." (PMID 35205313, 2022). "As a third characteristic of genomic instability associated with HRD, Popova and colleagues found the number of LSTs, defined as a chromosomal break between flanking regions larger than 10 Mb, to be a robust indicator of BRCA1/2 mutational status in breast cancer patients." (PMID 36077694, 2022). "The most common gene mutations associated with breast cancer are BRCA1 and BRCA2 mutations." (PMID 37435457, 2022). "For example, in breast cancer, BRCA1/2 loss of function is a primary driver." (PMID 35541919, 2022). "Among females who decline or defer surgery, early detection options for female carriers of a disease-causing BRCA1/2 variant usually comprise of a combination of routine mammograms and breast MRIs for breast cancer risks, which are effective at detecting breast cancer among BRCA1/2-positive females." (PMID 36353115, 2022).
breast cancer (continued). "After alignment of the forward sequence of the amplified BRCA1 gene to the forward sequence of the wild type of BRCA1 gene, a heterozygous allele, c.34311A>C had the highest frequency of occurrence in both breast cancer participants and apparently healthy participants (Annex 2)." (PMID 36942145, 2022). "Furthermore, we were unable to collect sufficient information that appears to be significant prognostic factors for breast cancer, such as BRCA1/2 mutations." (PMID 35912097, 2022). "Interestingly, the combination of DDX3 inhibitor RK-33 and PARP inhibitor Olaparib causes SL in BRCA1-proficient breast cancer." (PMID 36761420, 2022). "Likewise, in the context of PD-L1 expression mediated by HRD, BRCA1 mutated breast cancer has been demonstrated to have a higher PD-L1 tumor score than BRCA2 mutated, even though clinical efficacy is inferior." (PMID 35211121, 2022). "Clinical studies of PARP inhibitors in BRCA1/2-associated breast cancer." (PMID 35806485, 2022). "However, in another case, the mTOR signaling pathway played a role in accelerating DNA damage caused by deletion of the breast cancer-related gene BRCA1." (PMID 36147481, 2022). "BRCA1 germline mutation carriers are predisposed to breast cancers." (PMID 35118379, 2022). "Poly(adenosine diphosphate-ribose) polymerase inhibitors have recently been shown to be effective for patients with human epidermal growth factor receptor 2—negative (HER2−) advanced breast cancer (ABC) who have a germline mutation in their breast cancer susceptibility gene 1 or 2 (BRCA1/2mut)." (PMID 36358816, 2022). "Women who have an increased risk of developing breast cancer due to mutations in cancer susceptibility genes (i.e., BRCA1, BRCA2, PALB2, ATM, and CHEK2) or a familial predisposition undergo adapted screening programs compared to women who are at population risk." (PMID 36293255, 2022). "Breast cancer-associated genes 1 and 2 (BRCA1 and BRCA2) are tumor suppressor genes encoding a large protein that is involved in many essential biological processes, including DNA damage repair, cell cycle checkpoints, chromatin remodeling, transcriptional regulation, and protein ubiquitination." (PMID 35573021, 2022). "Breast cancers arising in Black women frequently share features that are common among BRCA1-associated cancers, such as younger age of onset, high tumor grade, and negative hormone receptor status, which all contribute to disparate breast cancer mortality rates." (PMID 35752812, 2022). "Background and Objectives: BRCA 1 and 2 mutations have a cumulative risk of developing ovarian cancer at 70 years of 41% and 15%, respectively, while a cumulative risk of breast cancer by 80 years of age was 72% for BRCA1 mutation carriers and 69% for BRCA2 mutation carriers." (PMID 35888662, 2022). "Notably, hereditary breast cancer is often associated with mutations in tumor suppressor BRCA1 and BRCA2 genes." (PMID 36139526, 2022). "In conclusion, this study confirms that, aside from female breast and ovarian cancers, BRCA1/2 PVs are associated with increased risks of breast cancer in men, and pancreatic and stomach cancers in both sexes, and that only BRCA2 carriers are at elevated prostate cancer risk." (PMID 35077220, 2022). "The mechanism by which CNV deletions overlapping SULT1A1 were associated with lower BRCA1-associated breast cancer risk may be linked to the production of potentially toxic catechol oestrogens by the Cytochromes P450 (CYP) enzymes." (PMID 36203093, 2022). "In addition, there are no prospective trials comparing different cancer risk–reducing strategies in patients with breast cancer that tested positive for the BRCA1 and BRCA2 pathogenic variants who were treated with BCT at the first event." (PMID 36580360, 2022).